SOD1 (superoxide dismutase 1)
Diseases named in the same sentence as SOD1 in open-access papers (continued):
Sharing a sentence is not in itself a finding about the gene and the disease.
amyotrophic lateral sclerosis (continued). "As β2m can promote nerve regeneration, we investigated its potential role in amyotrophic lateral sclerosis (ALS) by investigating its expression level as well as the effect of genetically removing β2m on the disease process in mutant superoxide dismutase 1 (SOD1G93A) mice, a model of ALS." (PMID 24368896, 2013). "Mutations in the Cu/Zn superoxide dismutase gene (SOD1) are responsible for 20% of familial forms of amyotrophic lateral sclerosis (ALS), and mutant SOD1 has been shown to have increased surface hydrophobicity in vitro." (PMID 24256636, 2013). "In patients with amyotrophic lateral sclerosis, PDI was found to be colocalized with SOD1 in neuronal cytoplasmic inclusions." (PMID 23061969, 2012). "In a murine model of amyotrophic lateral sclerosis (ALS, SOD1(G93A) mice), memantine treatment (10 mg/kg b.i.d. s.c. starting on postnatal day 70 until end point) caused a significant, but very moderate delay in disease progression and also moderately increased the life span." (PMID 19305788, 2008). "Tofersen is a gene-targeted therapy for superoxide dismutase 1 (SOD1)-associated amyotrophic lateral sclerosis (ALS), but neurofilament light chain (NfL) may not fully capture the biological response to treatment." (PMID 42196191, 2026). "Similarly, in amyotrophic lateral sclerosis (ALS), siRNA against SOD1 delays neurodegeneration and prolongs survival in transgenic mouse models." (PMID 41304744, 2025). "While we have identified a novel role for a silent potassium ion channel subunit in driving amyotrophic lateral sclerosis–related neurodegeneration, this does not explain the altered membrane excitability previously identified in SOD1(A4V) MNs." (PMID 38911266, 2024). "We found that the survival of SOD(A4V) amyotrophic lateral sclerosis MNs was significantly increased by KNCB2 shRNA knockdown when compared to SOD1(A4V) MNs with no KNCB2 knockdown." (PMID 38911266, 2024). "Furthermore, ASOs have shown promising efficacy in targeting Huntington's gene (HTT) for Huntington's disease (HD), targeting SOD1 and C9ORF72 for amyotrophic lateral sclerosis (ALS), and targeting MAPT (TAU) for AD." (PMID 39226164, 2024). "For instance, exosomal superoxide dismutase 1 (SOD1), exosomal dipeptide-repeat proteins (DPRs), exosomal TAR DNA-binding protein (TARDBP), and fused in sarcoma (FUS) have all been found to affect the spread of amyotrophic lateral sclerosis." (PMID 36834471, 2023). "A number of proteins has been explored as potential fluid biomarkers for frontotemporal dementia and amyotrophic lateral sclerosis, particularly those relating to frontotemporal dementia/amyotrophic lateral sclerosis brain pathology, e.g. TDP-43, tau, C9ORF72 or SOD1." (PMID 35202463, 2022). "For example, alpha-synuclein in Parkinson’s disease; amyloid-beta (Aβ) and hyperphosphorylated tau (p-tau) in Alzheimer’s disease; mutant huntingtin proteins in Huntington’s disease, and mutant superoxide dismutase 1 (SOD1) and TAR DNA binding protein 43 (TDP-43) in amyotrophic lateral sclerosis." (PMID 34440645, 2021). "Intrathecal delivery of AAVs containing an artificial miRNA suppressing superoxide dismutase 1 (SOD1) (a genetic cause of familial amyotrophic lateral sclerosis (ALS)), was shown to be efficient in SOD1 gene silencing in nonhuman primates, yet it did induce peripheral immune responses." (PMID 34742333, 2021). "Amyotrophic lateral sclerosis (ALS) and frontotemporal dementia (FTD) share a common mechanism for mitochondrial toxicity and neurodegeneration caused by protein misfolding and aggregation of mutant superoxide dismutase 1 (SOD1), TAR DNA-binding protein 43 (TDP-43), and RNA-binding protein FUS." (PMID 33922020, 2021). "To test this approach, we selected a model of amyotrophic lateral sclerosis (ALS), in which astrocytes expressing mutant superoxide dismutase-1 (mutSOD1) kill wild-type motor neurons (MNs) by an unknown mechanism." (PMID 33149111, 2020).
amyotrophic lateral sclerosis (continued). "The neuromuscular disorder amyotrophic lateral sclerosis (ALS) is characterized by protein inclusions formed by either TAR DNA-binding protein of 43 kDa (TDP-43), Cu/Zn superoxide dismutase (SOD1), or fused in sarcoma (FUS), in both upper and lower motor neurons." (PMID 31736708, 2019). "In addition, studies showed that oligomerization of superoxide dismutase 1 catalyzed by TG2 induced activation of BV-2 microglia, accelerating neuroinflammation in amyotrophic lateral sclerosis (ALS)." (PMID 30545030, 2018). "In addition, inhibition of an upstream activator of the NFκB pathway, Rho kinase, with Fasudil modulates microglial activation, reduces microglial infiltration to the spinal cord and improves functional outcome in the SOD1 mutant mouse model of amyotrophic lateral sclerosis (ALS)." (PMID 27446913, 2016). "Amyotrophic lateral sclerosis (ALS), which appears to spread through the neuroaxis in a spatiotemporally restricted manner, is linked to heritable mutations in genes encoding SOD1, TDP-43, FUS, C9ORF72, or can occur sporadically without recognized genetic mutations." (PMID 26926802, 2016). "Impaired microglial function is also reported in amyotrophic lateral sclerosis (ALS), where microglia derived from mutant superoxide dismutase 1 (SOD1) mouse, an established disease model of ALS, induce more oxidative stress and cause higher neuronal loss compared with wt microglia." (PMID 23596391, 2013). "For instance, an LTR12C repeat, comprising part of the long noncoding RNA BC041449 that is located directly upstream of the amyotrophic lateral sclerosis gene SOD1, is occupied by CTCF in Tc1-mouse liver, but not in human." (PMID 23246434, 2013). "As aging is the greatest risk factor for developing neurodegenerative diseases such as Amyotrophic Lateral Sclerosis (ALS), we were interested in determining if DAF-2 signaling modifies disease pathology in mutant superoxide dismutase 1 (SOD1) expressing C. elegans." (PMID 22457769, 2012). "Accordingly, crossing of mutant SOD1 expressing mice, a model of amyotrophic lateral sclerosis (ALS), on a tau knockout background, does not prevent weight loss and death." (PMID 22720190, 2012). "Based on the identification of single point-mutations in the gene encoding superoxide dismutase 1 (SOD1) in about 3% of the patients with amyotrophic lateral sclerosis (ALS), mice carrying 23 copies of the human SOD1G93A transgene are considered the standard model for therapeutic studies of ALS." (PMID 20361020, 2010). "In amyotrophic lateral sclerosis, surrounding wild-type non-neuronal cells can prevent the degeneration of SOD1 mutant motor neurons, and the genotype of the motor neurons themselves appears to have no bearing on their probability of survival." (PMID 16103921, 2005). "In a rodent model of amyotrophic lateral sclerosis (ALS), ISRIB alleviated ER stress and enhanced the survival of G93A SOD1-expressing neurons, in contrast to GSK2606414 treatment." (PMID 39995125, 2025). "Using this model, we investigated amyotrophic lateral sclerosis (ALS) and replicated ALS-specific NMJ cytopathies with SOD1 mutant and corrected isogenic iPSC lines." (PMID 39863573, 2025). "Post-mortem examination of spinal cord tissue from amyotrophic lateral sclerosis (ALS) patients consistently reveals the presence of TDP-43-, FUS- or SOD1- and ubiquitin-positive inclusions comprised of insoluble proteinaceous material." (PMID 38879591, 2024). "A quantitative proteomics study comparing brain-derived EVs from a nontransgenic (NTg) and a transgenic amyotrophic lateral sclerosis (ALS) animal model indicated that astrocyte- and neuron-derived EVs from ALS animal models carry a misfolded and aggregated pathogenic protein, SOD1." (PMID 36140248, 2022).
amyotrophic lateral sclerosis (continued). "Amyotrophic Lateral Sclerosis (ALS), a fatal neurodegenerative disease affecting the upper and lower motor neurons in the motor cortex and spinal cord, could be ameliorated by reducing the levels of superoxide dismutase I (SOD1)." (PMID 34361170, 2021). "Indeed, we and others have previously reported that GFP-LC3 can be used to monitor the autophagic status as well as disease progression in a GFP-LC3-expressing animal model of amyotrophic lateral sclerosis (ALS); i.e., human mutant SOD1-expressing transgenic mice." (PMID 32511278, 2020). "The only exception might be amyotrophic lateral sclerosis (ALS) that affects a mitochondrial protein, superoxide dismutase 1 (Sod1)—although Sod1 has a dual localization in the cytosol and in the intermembrane space and the aggregated material likely also accumulates in the cytosol." (PMID 32046155, 2020). "Likewise, rilmenidine failed to ameliorate the disease progression in a SOD1 transgenic mouse model of amyotrophic lateral sclerosis." (PMID 30309855, 2018). "Misfolded aggregates of superoxide dismutase 1 (SOD1) and transactive response DNA binding protein 43 kDa (TDP-43) are characteristic of amyotrophic lateral sclerosis (ALS)." (PMID 30065623, 2018). "Finally, familial amyotrophic lateral sclerosis (ALS) may result from mutations in the genes for TDP43, FUS, C9ORF72 and, classically, SOD1." (PMID 26035384, 2015). "Importantly, SOD1 is a hallmark gene in amyotrophic lateral sclerosis (ALS) and while there is no direct link between AD and ALS, our findings suggest that converging mechanisms such as oxidative stress and protein misfolding may pinpoint drug repurposing opportunities for both diseases." (PMID 41404291, 2025). "In amyotrophic lateral sclerosis (ALS), difficulties arise in the interaction between the copper chaperone of superoxide dismutase (CCS) and mutant copper-zinc superoxide dismutase (SOD1)." (PMID 38605864, 2024). "We demonstrate the repeatability of our PySeq2500 automated 4i protocol by comparing staining of spinal cord sections from the SOD1-G93A mouse model of amyotrophic lateral sclerosis (ALS) and nontransgenic control animals processed in parallel." (PMID 35332182, 2022). "Recently, it has been proposed that this mechanism also characterizes Amyloid-β (Aβ), tau, α-synuclein, SOD1, TDP-43, and huntingtin, involved in AD, PD, amyotrophic lateral sclerosis (ALS), frontotemporal lobar degeneration, and Huntington’s disease, respectively." (PMID 35416570, 2022). "Surprisingly, NAKα3 was also later reported to serve as a toxic target of misfolded protein assemblies, such as α-synucleins, superoxide dismutase 1 (SOD1), and tau, leading to other neurodegenerative diseases such as Parkinson'’s disease and amyotrophic lateral sclerosis (ALS)." (PMID 34458695, 2021). "Therefore, we currently extend our experiments with anle138b to Abeta, tau, SOD1 and TDP43 aggregation important for AD, frontotemporal dementia (FTD), and amyotrophic lateral sclerosis (ALS)." (PMID 23604588, 2013). "Similarly, unlike patients with amyotrophic lateral sclerosis (ALS), patients with HD also present with no superoxide dismutase 1 gene deletion." (PMID 35178023, 2021). "This oxidative property is likely related to the pathogenesis of amyotrophic lateral sclerosis (ALS); however, the mechanism by which Cu2+ re-binds to the denatured (E,E)-SOD1 has not been elucidated, since the concentration of free copper ions in cells is almost zero." (PMID 32784718, 2020). "In an amyotrophic lateral sclerosis (ALS) mouse model carrying a mutant superoxide dismutase 1 (SOD1G93A) 24HC also decreased NO production, but led to an opposite effect on neuromuscular transmission, because the role of NO is likely reversed in ALS mice as compared to wild type mice." (PMID 30823359, 2019).
amyotrophic lateral sclerosis (continued). "Finally, BNN27 was neuroprotective in a co-culture of mouse motor neurons with human astrocytes from amyotrophic lateral sclerosis (ALS) patients, however, it did not improve several clinical characteristics of the SOD1 mouse model of the disease." (PMID 30006508, 2018). "The receptor p75 has also been implicated in retrograde degenerative signaling in motor neurons of superoxide dismutase 1 mutant mice (SOD1G93A), which undergo axon degeneration and eventual motor neuron apoptosis and have been used as a model for amyotrophic lateral sclerosis (ALS)." (PMID 32714573, 2017). "In Amyotrophic Lateral Sclerosis (ALS), the genetic removal of the mutant protein SOD1 in cell populations that are not usually vulnerable to the disease, such as astrocytes and microglia, was sufficient to delay the progression of the symptoms." (PMID 27065789, 2016). "Pairwise interactions between SOD1, TDP-43 and ubiquitin-binding protein 62/sequestosome 1 (p62) proteinopathies have been reported in multiple transgenic cellular and animal models of amyotrophic lateral sclerosis (ALS), however patient data is lacking." (PMID 36008843, 2022). "However, such interactions for the case of Cu/Zn superoxide dismutase (SOD1) protein, which is related to fatal neurodegenerative disorder amyotrophic lateral sclerosis (ALS), have not been explored yet." (PMID 22216152, 2011).
diabetes (497 papers, 2007 to 2026). "The loss of Sod1 was associated with abnormal lipid metabolism, and SOD1 human polymorphisms were also linked to incidences of diabetes and obesity." (PMID 36834640, 2023). "In vivo study confirmed that andrographolide promoted the expressions of Nrf2, Cat, and Sod1, suggesting andrographolide confers antioxidant defense against diabetes-associated oxidative stress." (PMID 32774682, 2020). "Interestingly, the association between ICH volume and SOD1 expression increases slightly when adjusting for diabetes mellitus, but remains unchanged when adjusted for every other covariates." (PMID 33564466, 2021). "In addition, the genetic association between polymorphism in the (+35A/C) SOD1 gene and type 2 diabetes mellitus has also been studied." (PMID 27190652, 2016). "Moreover, SODs protect from the development of diabetes since it was shown that increased expression of SOD1 in pancreatic islet β cells is associated with increased resistance to alloxan-induced diabetes and increased SOD activity leads to increased resistance to streptozocin-induced diabetes." (PMID 32709094, 2020). "Oral administration of EeSs boosted the expression of Sod1, Cat, Gpx-1, Hmox-1, and Nqo-1 mRNA levels in the diabetic mice liver, suggesting that EeSs has a strong antioxidant potential to quince free radicals and hence the ability to prevent diabetes-associated complication." (PMID 28607575, 2017). "Compared with Ctrl mice, the expression of Nrf2, HO-1 and SOD1 proteins in kidney of diabetes mice were significantly reduced (p < 0.01)." (PMID 40176887, 2025). "Tripdiolide markedly escalated the expression of Nrf2 (by 72.2%), HO-1 (by 62.9%), and SOD1 (by 70.0%) in the kidney of diabetes mice (p < 0.05)." (PMID 40176887, 2025). "Deficiencies in antioxidant defenses against ROS described in diabetes included antioxidant enzyme such as SOD1, PRDX1, Hmox1 and antioxidants, thioredoxin 1 (Txn1)." (PMID 37337262, 2023). "In diagnosing or treating diabetes, a study found that increased levels of SOD1 protein helped reduce the apoptosis induced by maternal diabetes." (PMID 37759978, 2023). "In our research, PZH facilitates diabetic wound healing, the expression of Nrf2, HO-1, and SOD-1 were upregulated in the wound tissue of the diabetes models treated with topical or intragastric PZH." (PMID 36713837, 2023). "AGE/RAGE signaling increases oxidative stress to promote diabetes-mediated vascular calcification through activation of Nox-1 and decreased expression of SOD-1." (PMID 36979367, 2023). "The western blotting results showed that the protein expression levels of Nrf2 and its downstream targets HO-1 and SOD-1 were upregulated in the wound tissue of the diabetes models treated with topical or intragastric PZH compared with the control groups." (PMID 36713837, 2023). "We did not observe differences in the relative amount of HMGB1, S100B, S100A6 and SOD1 proteins in SN harvested from diabetic and control mice at six months after diabetes induction in our experiment (P ≥ 0.05)." (PMID 37462767, 2023). "In the present study, the expression of SOD1/cytosolic SOD/copper zinc (CuZn-SOD) in immunohistochemistry was gradually decreased following the long-term duration of diabetes in the DM2 and DM4 groups." (PMID 36818894, 2022). "A well-known example is SOD1 related to neuroinflammation, hyperthyroidism, hypertensive disease (associated also with GJA1), diabetes mellitus (associated also with IGF2BP2) and depressive disorders (associated also with S100B)." (PMID 34570756, 2021). "Expectedly, SOD1 was the gene with the highest number of GDAs including nerve degeneration hyperthyroidism, hypertensive disease, diabetes mellitus and depressive disorders, which are known comorbidities in Down syndrome." (PMID 34570756, 2021).